TNF (tumor necrosis factor)
Diseases named in the same sentence as TNF in open-access papers (continued):
Sharing a sentence is not in itself a finding about the gene and the disease.
non-alcoholic fatty liver disease (continued). "TNF-α, ALT, and glucose are the major markers of liver inflammation and injury caused by non-alcoholic fatty liver disease (NAFLD)." (PMID 32370249, 2020). "Genistein, a soy phytoestrogen, has been reported to show anti-inflammatory effects through reduction of TNF-α and IL-1β mRNA expression in nonalcoholic fatty liver disease db/db mice." (PMID 30764536, 2019). "In a study on rats with non-alcoholic fatty liver disease, 200 mg/day propolis reduced TNF-α and IL-6, with effects attributed to the anti-inflammatory activity of propolis." (PMID 31717277, 2019). "In that study, the reduction in CRP and TNF-α as well as other liver enzymes was measured after the treatment of non-alcoholic fatty liver disease." (PMID 29564059, 2018). "Anti-TNF-α agents have been tested in advanced stages of severe alcoholic hepatitis and non-alcoholic fatty liver disease." (PMID 30060508, 2018). "Increased TNF-α production not only contributes to chronic alcoholic liver injury but also influences the nonalcoholic fatty liver disease process." (PMID 29109622, 2017). "TNF-α level was elevated significantly in nonalcoholic fatty liver disease and NASH in both humans and animals." (PMID 26463841, 2015). "In agreement, several previous studies reported that anti-TNF-α therapy is helpful to inhibit the development of steatohepatitis in patients with severe alcoholic steatohepatitis and nonalcoholic fatty liver disease in rodents and humans." (PMID 25739082, 2015). "KEGG pathways such as IL-17 signaling, TNF signaling, non-alcoholic fatty liver disease, and pathways in cancer were significantly enriched, consistent with the module’s role in amplifying inflammatory cascades, metabolic imbalance, and immune-mediated tissue injury." (PMID 41226767, 2025). "This is consistent with previous studies showing baicalin to have anti-inflammatory effects in vitro in a mouse macrophage cell line and in a rat model of hepatotoxicity and a mouse model of non-alcoholic fatty liver disease where it reduced serum TNF-α levels." (PMID 38503930, 2024). "Likewise, further data suggest a potential role of biological treatments used in maintenance and remission periods, such as TNF-α inhibitors, as a protective factor against nonalcoholic fatty liver disease in patients with IBD." (PMID 39605944, 2024). "The analysis indicated that the pharmacodynamic differences might be linked to pathways such as the PI3K/Akt signaling pathway, insulin signaling pathway, nonalcoholic fatty liver disease, TNF signaling pathway, and FoxO signaling pathway." (PMID 39201413, 2024). "The constant, systemic inflammatory process and high concentrations of TNF-α may contribute to the progression of chronic liver inflammation in non-alcoholic fatty liver disease (NAFLD)." (PMID 37568441, 2023). "While there were inconsistencies between clinical trials and preclinical research, both study types revealed that resveratrol significantly reduced tumor necrosis factor-α levels, further supporting its protective effect against nonalcoholic fatty liver disease." (PMID 37767399, 2023). "In addition, the altered lipid metabolism was reported to be linked with many signaling pathways, such as TNF signaling, Wnt signaling, and MAPK, leading to worse outcomes that included T2D and non-alcoholic fatty liver disease." (PMID 36034923, 2022). "KEGG pathway enrichment analysis was also performed using these DEGs and revealed that the non-alcoholic fatty liver disease pathway (hsa04932) and the tumor necrosis factor (TNF) signaling pathway (hsa04668) terms were enriched for 24 genes and 23 genes, respectively." (PMID 34290609, 2021). "Adipokines, such as tumor necrosis factor alpha, IL‐6, leptin, and adiponectin produced by adipose tissue, are closely involved with hepatic lipid deposition, inflammation, fibrosis, and carcinogenesis in nonalcoholic fatty liver disease." (PMID 34463983, 2021).
non-alcoholic fatty liver disease (continued). "Furthermore TNF-α expression was positively correlated with non-alcoholic fatty liver disease (NAFLD), confirming NAFLD as an inflammatory disease." (PMID 33858417, 2021). "Pentoxifylline can decrease the AST (Aspartate aminotransfrase) and ALT (Alanin aminotransfrase) levels and its anti-TNF-α effect also improves symptoms of liver tissue in patients with NALFD (Non-alcoholic steatohepatitis)/NASH Non-alcoholic fatty liver disease." (PMID 24106597, 2013). "In methionine-choline deficiency (MCD)-induced Non-Alcoholic Fatty Liver Disease (NAFLD), the OCTN2 substrate betaine might reduce liver inflammation and damage, at least partly, by improving the balance between proinflammatory (TNF, IL-6) and anti-inflammatory (IL-10, TGF-β) cytokines." (PMID 38672410, 2024). "thomsonii polysaccharide (RPP-2), which has an α-D-1,3-glucan structure, can slow the release of TNF-α in HFD-induced NAFLD mice, reshape the Th17/Treg balance, and potentially treat nonalcoholic fatty liver disease." (PMID 39202931, 2024). "Aucubin also prevented the elevation of MMP-9, MCP-1, apoC-III, ICAM-1, VCAM-1, TNF-α, IL-1β, and IL-6 levels after stimulation by apoC-III in 3T3-L1 cells and in mice with tyloxapol-induced nonalcoholic fatty liver disease (NAFLD)." (PMID 37241895, 2023). "In addition, the levels of TG, TC, and TNF-α reduced by 33.3%, 16.7%, and 39.8%, respectively, suggesting the potential value of quercetin in treating non-alcoholic fatty liver disease (NAFLD)." (PMID 38004496, 2023). "MAIT cells promote M2 polarization of macrophages in non-alcoholic fatty liver disease (NAFLD) by the production of regulatory cytokines (high production of IL-4, but reduced IFN-γ and TNF levels)." (PMID 36875139, 2023). "Data analysis showed that targets were significantly enriched in multiple pathways, such as the TNF signaling pathway, MAPK signaling pathway, nonalcoholic fatty liver disease (NAFLD), and Toll-like receptor signaling pathway." (PMID 35422858, 2022). "ASK1 is a pivotal kinase in the TNF and Fas signaling pathway that induces apoptosis, and inactivation of the liver-specific ASK1 improves non-alcoholic fatty liver disease (NAFLD)." (PMID 36017335, 2022). "In fact, curcumin improved the severity of patients affected by non-alcoholic fatty liver diseases (NAFLD) disease decreasing the serum concentrations of inflammatory cytokines and chemokines such as TNF-α and MCP-1." (PMID 33477354, 2021). "The associations between serum levels of melatonin and concentrations of tumor necrosis factor (TNF)-a and interleukin (IL)-6 were assessed among patients with different degrees of non-alcoholic fatty liver disease." (PMID 34221262, 2021). "Among other pathways that are significantly enriched, we found “Non-alcoholic fatty liver disease (NAFLD)”, “TNF-signaling pathway”, “NOD-like receptor signaling pathway” etc." (PMID 27257970, 2016). "The non-traditional cardiovascular risk factors that we studied were the following: hs-CRP, TG/HDL ratio, ApoA1, ApoB, ApoB/ApoA1 ratio, leptin, adiponectin, homocysteine, IL-2, IL-4, IL-6, IL-10, IL-17A, TNF-α and INF-γ, and non-alcoholic fatty liver disease (NAFLD)." (PMID 37892418, 2023). "We identified the lncRNA uc.333 using an lncRNA microarray and then used quantitative real-time polymerase chain reaction to analyze its expression in the livers of nonalcoholic fatty liver disease (NAFLD) patients, db/db mice, high-fat diet–fed mice, IL-6-treated mice, and TNF-α-treated mice." (PMID 32303004, 2020). "Inflammatory factors, including tumor necrosis factor-α (TNF-α), interleukin-1 β (IL-1β), interleukin- 6 (IL-6), transforming growth factor-β (TGF-β), are involved in drug-induced liver injury, cholestasis, alcoholic and non-alcoholic fatty liver diseases, and other chronic liver disease processes." (PMID 34366845, 2021).
non-alcoholic fatty liver disease (continued). "Higher hepatic TNF-α (P<0.0001) and IL-10 (P=0.001) mRNA levels were found in RBD-challenged mice, although without detectable non-alcoholic fatty liver disease." (PMID 32401929, 2020).
bladder cancer (149 papers, 2003 to 2026). "Anti‐TNF therapy of autoimmune disorders has been associated with an increased risk for malignancies including bladder cancer." (PMID 38553868, 2024). "For example, Rpph1 is enriched in bladder cancer and linked to immune-related pathways, such as IL-1, TNF-α, Il-17 signaling, and M2 macrophage polarization." (PMID 39769061, 2024). "TNF-α is involved in angiogenesis by the regulation of thymidine phosphorylase, whereas the enzyme is associated with bladder cancer progression." (PMID 33923108, 2021). "Compared to SNPs of TNF-α, -308 G/A polymorphism was investigated and found to be related to several cancers, including breast, gastric, and bladder cancers." (PMID 29951534, 2018). "A Korean study also reported that the TNF-α -308 G/A polymorphism was significantly associated with the tumor stage and grade of bladder cancer." (PMID 29951534, 2018). "TNF-α was shown to stimulate bladder cancer cells to produce MMP-9, which has been implicated in tumor invaαsion and metastasis." (PMID 23637926, 2013). "Conversely, the del/del genotype can promote the proliferation of bladder cancer through the transcriptional activation of TNF-α caused by the inhibitory effect of the del/del genotype on the formation of p50 homodimers." (PMID 23977085, 2013). "The purpose of this study is to assess the role of tumour necrosis factor (TNF) polymorphisms in the risk of developing bladder cancer and effect on tumour stage, grade and progression." (PMID 12966432, 2003). "We have shown for the first time a significant association of the TNF polymorphisms TNF+488A and TNF−859T and risk of bladder cancer." (PMID 12966432, 2003). "The role of TNF polymorphisms in the risk of bladder cancer, bladder cancer phenotype and subsequent tumour behaviour was assessed in this study." (PMID 12966432, 2003). "In conclusion, we have demonstrated for the first time a TNF polymorphism association with risk of bladder cancer and grade of tumour at presentation." (PMID 12966432, 2003). "In all, seven single-nucleotide polymorphisms in TNF were studied in 196 bladder cancer patients and 208 controls using a PCR-SSP genotyping technique." (PMID 12966432, 2003). "It was seen that there was a significant association of two polymorphisms in TNF with bladder cancer: the TNF+488A allele was found in 28.1% of patients compared with 14.9% of controls (P=0.0012)." (PMID 12966432, 2003). "In conclusion, a significant association between TNF polymorphisms TNF+488A and TNF−859T and risk of bladder cancer was detected in this study." (PMID 12966432, 2003). "As widely reported, TLSs in the bladder also form during the course of normal aging due to increased systemic levels of TNF-α, chronic inflammatory conditions of the urogenital tract such as those observed in interstitial cystitis-associated Hunner lesions and bladder cancer." (PMID 35505436, 2022). "GRβ is induced by inflammatory pathways such as TNFα and NF-κB, suggesting that it may have a paramount role in inflammation that is associated with bladder cancer." (PMID 26347776, 2015). "Besides, they found expressional change of TNF-alpha was associated with angiogenesis of bladder tumor, especially in bladder cancer development." (PMID 22811589, 2012). "In addition to their role in the risk of bladder cancer, we investigated the role of TNF polymorphisms in tumour behaviour." (PMID 12966432, 2003). "If it affects the responsiveness of TNFα production to toxic stress, then this may explain the relation to risk of bladder cancer and higher grade and determine the effectiveness of intravesical BCG." (PMID 12966432, 2003). "In addition to the association of TNF+488A and TNF−859T with risk of bladder cancer, we have shown for the first time a very strong linkage disequilibrium between these two sites in bladder cancer patients, normal controls and melanoma patients." (PMID 12966432, 2003).
bladder cancer (continued). "The importance of TNFα in bladder cancer pathogenesis raises the possibility that variation in the gene for TNFα (TNF) may predispose to risk of bladder cancer or alter subsequent tumour behaviour." (PMID 12966432, 2003). "For IL-6 and TNF-α, the simultaneous, significant elevation of these two proinflammatory cytokines implies that bladder cancer exists within an environment of persistent inflammation." (PMID 41614883, 2025). "In our study, we aimed to investigate the relationship between miRNA-21, miRNA-155, miRNA-34a, IL-6, TGF-β, and TNF-α expression levels and serum trace element levels in the development and progression of bladder cancer." (PMID 41614883, 2025). "First, we only conducted bioinformatics analysis and qPCR without performing histological, cytological, or animal experiments to validate the regulation of the TNF signaling pathway in bladder cancer cells by Disitamab Vedotin in vivo and in vitro." (PMID 40699768, 2025). "Specifically, tumor necrosis factor-alpha (TNF-α) drives bladder cancer metastasis via METTL3-mediated m6A modification of cytoplasmic Linker associated protein 2 (CLASP2)." (PMID 40986143, 2025). "In summary, the results of these bioinformatics analyses indicate that the TNF signaling pathway is the key pathway regulated by Disitamab Vedotin in bladder cancer cells." (PMID 40699768, 2025). "Our data indicate that TAMs are capable of inducing GSTO1 expression in bladder cancer by secreting tumor necrosis factor‐alpha (TNF‐α)." (PMID 38750006, 2024). "The present study showed that secretory TNF‐α from TAMs induced GSTO1 expression in bladder cancer cells, which in turn contributed to the generation of large EVs for cisplatin efflux." (PMID 38750006, 2024). "The aberrant high-level of BACH1-IT2 in bladder cancer significantly inhibited immune activation in our in vitro co-culture system as indicated by secretion of both IL-2 and TNF-α." (PMID 38468240, 2024). "Compared with those of the healthy control, cystitis and upper urinary tract cancer samples, the proteins of the bladder cancer samples were more active in the protein-activated cascade, tumor necrosis factor and neutrophils." (PMID 38410113, 2024). "Specifically, CB1R activation has been associated with increased TNFα secretion in human bladder carcinoma cells, whereas CB1R antagonism was reported to inhibit TNFα production in the inflamed small intestine in rats." (PMID 35647939, 2023). "The only earlier published results of MSC effects on 5637 and HT-1376 bladder cancer cell lines by ELISA reported cell line-dependent effects on IL-1B, IL-6, IL-8, TNFα, GM-CSF, MCP-1, TGF-β, and RANTES." (PMID 37781195, 2023). "In the LW and M group, the DEPs were enriched in disease and immune-related pathways, such as pathways for leukocyte transendothelial migration, NF-kappa B signaling, TNF signaling, and bladder cancer, among others." (PMID 36552219, 2022). "Increased TNFα can attenuate NF-κB activity in wogonin exposed leukemic cells and fisetin treatment in bladder cancer induces apoptosis through inhibition of NF-κB pathway." (PMID 36078142, 2022). "We also found GM-CSF and TNFα were highly secreted by T24 bladder cancer cell line by Bio-Plex Multiplex Immunoassays." (PMID 35386697, 2022). "Taken together, these results indicate that forced expression of HOTAIR or ProT in human bladder cancer cells enhances the expression of IL-6, TNF-α, and IL-1β." (PMID 36471329, 2022).
bladder cancer (continued). "Studies have reported that TNF-alpha induced MMP-9 expression in bladder cancer cells by activating the transcription factor NF-kappaB, which is involved in the p38 MAP kinase-mediated control of MMP-9 regulation." (PMID 34868913, 2021). "The meta-analysis showed that the −308 A/A+G/A genotype of TNF-α also correlated with the bladder cancer grade." (PMID 33923108, 2021). "In TNF-α-treated ADSCs cultured with the bladder cancer (BC) cell medium, the results showed that apoptosis ratio and OCT-4 and TLR2 genes which maintained the self-renewal ability of stem cells were decreased." (PMID 33924332, 2021). "Pathway and network analysis of differentially expressed proteins in HG bladder cancer using Ingenuity Pathway Analysis revealed numerous common proteins linked together, with IFN-γ and TNF as important hubs." (PMID 34947825, 2021). "Proinflammatory cytokines, such as IL-6, IL-8, and TNF-α, play critical roles in the pathogenesis of bladder cancer." (PMID 32315283, 2020). "The function enrichment analysis obtained 13 GO entries and 6 KEGG pathways, including bladder cancer, cancer pathways, chemical carcinogenesis, estrogen signaling pathway, TNF signaling pathway, and leukocyte transendothelial migration." (PMID 32849897, 2020). "BCG also induced a strong release of IFN‐γ, TNF‐α, IL‐1β, IL‐10, and IL‐12p70 in human bladder cancer cells." (PMID 30358081, 2019). "TNF-α-induced MMP9 expression is dependent on P38 signaling in human urinary bladder cancer 5637 cells or human monocytes." (PMID 31307477, 2019). "Although the TNF-α A/A genotype frequency was very low in Japanese (141 bladder cancer patients and 173 control subjects), the allelic frequency of patients (3.5%) was higher than that in controls (0.6%)." (PMID 29951534, 2018). "Intra-vesical instillation of Bacillus Calmette-Guérin (BCG) to treat early stages of bladder cancer triggered local inflammation and TNF release from recruited neutrophils." (PMID 28771230, 2017). "First, we treated the 5637 and T24 bladder cancer cell lines with TNF-α (50 ng/ml) for 0, 2, 3, 4 and 6 h." (PMID 28139689, 2017). "IL-6 was significantly increased in the material collected from patients affected by bladder cancer, whereas TNFα showed a tendency to be induced (p = 0.08)." (PMID 26927195, 2016). "Taken together, our study demonstrated that HCS induced-apoptosis in human bladder cancer was mediated by the activation Fas/Fasl and TNF-α/TNFR1." (PMID 25887782, 2015). "The TNF signaling pathway, leukocyte trans-endothelial migration and ascorbate, aldarate metabolism carbohydrate metabolism and Bladder cancer were the 4 significant enriched KEGG pathways." (PMID 26359664, 2015). "Although the role of chronic inflammation in the etiology of TCC of the bladder has not been well established, there is mounting evidence that proinflammatory cytokines play critical roles in the pathogenesis of bladder cancer, such as IL-6, IL-8 and TNF- α." (PMID 23637926, 2013). "Results showed that biharzial bladder cancer patients recored more significant elevation in serum XO, fructosamine, LDH, AST, ALT, hydroxyproline, IgE and TNF-α than in bladder cancer patients when compared to control ones." (PMID 21473769, 2011). "Table shows significant increase in serum XO enzyme activity, fructosamine, hydroxyproline, IgE, and TNF- α concentrations in bilharzial bladder cancer patients compared to non- bilharzial bladder cancer ones and control healthy patients." (PMID 21473769, 2011). "This macrophage-mediated killing of bladder cancer cells depends on both direct effector-target cell contact and release of soluble cytotoxic factors, such as TNF-α,IFN-γ, and NO, from macrophages." (PMID 20862387, 2010).